TRH (thyrotropin releasing hormone)
Diseases named in the same sentence as TRH in open-access papers (continued):
Sharing a sentence is not in itself a finding about the gene and the disease.
TSHomas (5 papers, 2008 to 2025). "Assessment of TSH alpha subunit and TRH stimulation tests can help in differentiating TSHomas from pituitary and peripheral resistance to thyroid hormones." (PMID 18307779, 2008). "Additionally, in contrast with patients with THRS, there is typically no increase in TSH or α-subunit after intravenous TRH (the TRH stimulation test) in patients with TSHomas." (PMID 40259920, 2025). "The TRH stimulation test has high-quality evidence for diagnosing TSHomas, showing abnormal TSH concentration responses in 90% of TSHoma patients—we could not perform this test because our hospital did not have the hormone in stock." (PMID 40506885, 2025).
Alzheimer disease (4 papers, 2018 to 2023). A progressive, neurodegenerative disease characterized by loss of function and death of nerve cells in several areas of the brain leading to loss of cognitive function such as memory and language. "The potential role of TRH as a neuroprotector involves using the peptide as a therapeutic agent in psychiatric illnesses such as Alzheimer’s disease." (PMID 37446225, 2023).
euthyroid sick syndrome (4 papers, 2013 to 2023). Abnormal thyroid function tests, low triiodothyronine with elevated reverse triiodothyronine, in the setting of non-thyroidal illness. "It is believed that these patients have intact response to TRH stimulation test in contrast to sick euthyroid syndrome." (PMID 26798547, 2015). "Patients with acute severe fungal infections may develop euthyroid sick syndrome, characterized by decreased levels of triiodothyronine and increased levels of normal thyroxine and thyrotropin-releasing hormone, as described in cases of paracoccidioidomycosis." (PMID 24159398, 2013).
Hashimoto thyroiditis (4 papers, 2012 to 2025). An autoimmune disorder caused by the production of autoantibodies against thyroid tissue. "The pathogenesis of PHPH is rooted in thyroxine deficiency, such as that seen in Hashimoto's thyroiditis, which triggers an increase in thyroid‐stimulating hormone‐releasing hormone (TRH) secretion." (PMID 39502127, 2024). "We performed large-scale, two-sample Mendelian randomization (MR) analyses to examine whether there was an association between TD (such as Graves’ disease (GD), Hashimoto’s thyroiditis (HT), thyroid cancer (TC), thyroid stimulating hormone (TSH), thyrotropin-releasing hormone (TRH), etc.)and AA." (PMID 39205687, 2024). "One study of 92 patients with Hashimoto’s thyroiditis on thyroid replacement looked at the TSH and l-thyroxine responses to administration of 500 mcg of thyrotropin releasing hormone (TRH)." (PMID 22551356, 2012).
Hyperglycemia (4 papers, 2022 to 2025). An increased concentration of glucose in the blood. "It is also believed that hyperglycemia has an effect on the TSH response to thyrotropin-releasing hormone and can influence the conversion of free thyroxine to free triiodothyronine in peripheral tissues." (PMID 37688711, 2024). "Conversely, hyperglycemia can have an effect on thyroid hormones by controlling TSH secretion from the hypothalamus, influencing conversion of fT4 to fT3 in peripheral tissues, and affecting the TSH response to thyrotropin-releasing hormone (TRH)." (PMID 36070417, 2022).
melanoma (4 papers, 2021 to 2023). A malignant, usually aggressive tumor composed of atypical, neoplastic melanocytes. "Different hormonal players of the HPT axis are thought to be involved in melanoma progression (i.e., TRH, TSH, and TH)." (PMID 36077430, 2022). "Altogether, these findings support the potential regulatory role of TRH in melanocyte function and melanoma progression." (PMID 36077430, 2022). "TRH can bind to the MC1R expressed in B16 melanoma cell lines, where it stimulates the production of c-AMP." (PMID 34068618, 2021). "Furthermore, it was shown that the expression of TRH was more likely to be present in dysplastic nevi than in normal nevi, and that dysplastic nevi from melanoma patients had a higher TRH expression compared to those of healthy subjects." (PMID 36077430, 2022). "In addition, experimental data suggest that, in addition to thyroid hormones, other hormonal players of the hypothalamic–pituitary–thyroid (HPT) axis, namely the thyrotropin releasing hormone and the thyrotropin, are likely to affect melanoma cells behavior." (PMID 36077430, 2022). "Indeed, Ellerhorst and colleagues demonstrated a stimulatory effect of low TRH concentrations on melanoma cells proliferation." (PMID 36077430, 2022). "The hypothesis that locally produced TRH could induce melanoma growth relies on its ability to bind and activate the melanocortin-1 receptor expressed in both melanocytes and melanoma cells." (PMID 36077430, 2022). "Moreover, TRH and its receptor have long been identified both in melanoma cell lines and in human tumor tissues." (PMID 34068618, 2021). "In addition, TRH expression is more pronounced in melanomas and dysplastic nevi than in benign nevi, suggesting that TRH may be involved in the development of melanoma cells, possibly acting in a paracrine or autocrine manner." (PMID 34068618, 2021). "All together, these observations have led to suppose that alterations of the hypothalamic–pituitary–thyroid (HPT) axis, such as reduced thyroid hormones (TH), increased thyroid stimulating hormone (TSH), or thyrotropin releasing hormone (TRH) levels, could promote melanoma growth." (PMID 36077430, 2022). "Although the pituitary thyrotropin-releasing hormone (TRH) does not enter the systemic circulation, the presence of immunoreactive TRH has been found in melanoma tissues, with its expression thought to be induced by low levels of TH as occurs in the hypothalamus." (PMID 36077430, 2022). "Moreover, it is important to emphasize that low-concentration TRH treatment leads to the proliferation of melanoma cells, an effect that could not be observed in cultured normal melanocytes." (PMID 35805166, 2022). "Additionally, it is important to emphasize that low-concentration TRH administration induces an increase in melanoma cell proliferation, an effect that could not be highlighted in cell cultures of melanocytes." (PMID 34068618, 2021).
acute myeloid leukemia (3 papers, 2022 to 2025). Acute myeloid leukemia (AML) is a group of neoplasms arising from precursor cells committed to the myeloid cell-line differentiation. "TRH has been found as a potential biomarker in breast cancer, acute myeloid leukemia (AML), and melanoma." (PMID 41465216, 2025).
alcoholism (3 papers, 1997 to 2018). "These early data suggest the possibility that alcohol intake is based in part on deficient extrahypothalamic TRH neural systems and offer the exciting prospect of the use of TRH analogs clinically in the treatment of alcoholism." (PMID 15706763, 1997). "Whatever the reason, it is of great interest that young nonalcoholic men with alcoholic fathers (who are at high risk for alcoholism themselves) also tend to have abnormal TSH responsiveness to TRH, usually a blunted response." (PMID 15706763, 1997). "The role of hormones, such as TRH, in the genesis of alcoholism is an exciting area of research; findings in this area may produce innovative treatments for the disorder." (PMID 15706763, 1997).
amenorrhea (3 papers, 2011 to 2025). The absence of menses in a woman who has achieved reproductive age. "Our patient had been diagnosed as having SCD and treated with TRH-tartrate for a long period until she subsequently started receiving another TRH agonist, taltirelin hydrate, and developed amenorrhea." (PMID 22152284, 2011). "We report the case of a patient who was treated with a TRH preparation for SCD who developed amenorrhea following a dose increase." (PMID 22152284, 2011). "We report the case of a patient being treated with a thyrotropin-releasing hormone preparation for spinocerebellar degeneration who developed amenorrhea after a dose increase." (PMID 22152284, 2011).
anorexia nervosa (3 papers, 2020 to 2021). A disorder most often seen in adolescent females characterized by a refusal to maintain a minimally normal body weight, an intense fear of gaining weight, a disturbance in body image, and, in postmenarcheal females, the development of amenorrhea. "In addition, fasting during illness (or in anorexia nervosa) further downregulates TRH release through decreased leptin signalling." (PMID 33585976, 2021).
bipolar depression (3 papers, 2011 to 2022). "This study showed rapid and significant improvement in bipolar depression symptoms with TRH within 24 h compared to placebo (52% vs. 12%)." (PMID 36421864, 2022). "Although we identified a placebo-controlled RCT of a single nocturnal dose of 500 mcg TRH (n = 10) compared to normal saline (n = 10), to evaluate the antidepressant response in 20 bipolar depression patients, we decided not to include it in the review, as it is not available for clinical practice." (PMID 36421864, 2022).
breast carcinoma (3 papers, 2019 to 2025). "For example, low expression of circulating thyrotropin releasing hormone (TRH) is associated with increased risk of lung, colon, prostate, and breast cancer." (PMID 31600974, 2019). "Among the key genes found in these enriched categories, TPSD1, FABP4, CARTPT, TRH, CSN3, and MMP9 stand out based on previously published data, which suggest their critical roles in cancer progression, including breast cancer." (PMID 40870889, 2025). "The remaining four have all been studied for their effects in the development and maintenance of human breast cancers (TNP1, FST, ANKRD40, TRH)." (PMID 33957863, 2021).
Cerebral ischemia (3 papers, 2009 to 2023). Restriction of arterial blood supply to the brain associated with insufficient oxygenation to support the metabolic requirements of the tissue. "The neuroprotective effects of TRH and its analogs have been showed in animal models of cerebral ischemia, cellular models of PD and AD." (PMID 30618632, 2018). "It has also been reported that TRH analogs also provide significant beneficial effects against cerebral ischemia." (PMID 19915665, 2009).
COVID-19 (3 papers, 2023 to 2025). A disease caused by infection with severe acute respiratory syndrome coronavirus 2. "The higher abundance of TRH in the positive COVID-19 group also indicates an endocrine imbalance in low-severity diseases, as reported here for the first time." (PMID 39595969, 2024). "The higher abundance of thyrotropin-releasing hormone in the COVID-19 positive group highlighted the endocrine imbalance in low-severity disease, as first reported here, underscoring the need for further studies in this area." (PMID 39595969, 2024). "Therefore, further studies are required to understand the role of TRH in the progression of mild-to-moderate COVID-19." (PMID 39595969, 2024). "We assessed the causal association of three COVID-19 phenotypes with insulin-like growth factor 1, estrogen, testosterone, dehydroepiandrosterone (DHEA), thyroid-stimulating hormone, thyrotropin-releasing hormone, luteinizing hormone (LH), and follicle-stimulating hormone." (PMID 36836216, 2023).
dementia (3 papers, 2013 to 2023). Loss of intellectual abilities interfering with an individual's social and occupational functions. "TRH is decreased in the hippocampus of AD patients and alterations in TSH or thyrotropin have also been implicated as a risk factor for AD and dementia." (PMID 30618632, 2018). "When added to fetal rats’ hippocampal cultured cells, TRH (200 nM, 10 min) stimulates the activity of MAPK and inhibits GSK3β, which prevents the phosphorylation of tau protein, a main trigger of the formation of neurofibrillary tangles associated with dementia in AD." (PMID 37446225, 2023). "Hence, TRH has a more widespread role as a central nervous system (CNS) transmitter, and the brain involution of the dementia process may lead to a widespread perturbation of neurotransmitters, together with TRH." (PMID 24171118, 2013).
Dyskinesia (3 papers, 2010 to 2018). A movement disorder which consists of effects including diminished voluntary movements and the presence of involuntary movements. "Our findings raise the possibility that the dyskinesias suffered by patients with PD following prolonged L-DOPA therapy are also correlated with spatially selective dysregulation of TRH within the striatum." (PMID 21085660, 2010). "Activation of signaling cascades related to TRH could thus be critically important for understanding the mechanisms giving rise to the occurrence of dyskinesias in parkinsonian conditions." (PMID 21085660, 2010). "Particularly relevant to the findings we report here are experiments suggesting that the behavioral patterns stimulated by increased intrastriatal TRH in intact non-primate mammals are akin to human dyskinesia." (PMID 21085660, 2010). "ProTRH immunostaining suggested that TRH peptide levels were almost absent in the dopamine-depleted striatum of control rats that did not develop dyskinesias, but in the dyskinetic rats, proTRH immunostaining was dramatically up-regulated in the striatum, particularly in the sensorimotor striatum." (PMID 21085660, 2010). "Above all, our study showed that TRH analog Taltirelin promoted DA release in the CNS in a mild and persistent manner, thus improving the motor function and relieving the PD-related abnormal electrical activities of PD rats without inducing dyskinesia in sub-chronic or high-dose use." (PMID 30555300, 2018).
epilepsy (3 papers, 2014 to 2025). A brain disorder characterized by episodes of abnormally increased neuronal discharge resulting in transient episodes of sensory or motor neurological dysfunction, or psychic dysfunction. "TRH and TRH analogs are also being evaluated for their therapeutic potential in areas of neuroprotection, psychiatric and mood disorders, narcolepsy and certain forms of epilepsy." (PMID 24860449, 2014). "He received a diagnosis of epilepsy and was treated with CBZ, CZP, VPA, and intramuscular thyrotropin-releasing hormone." (PMID 40755616, 2025).
Galactorrhea (3 papers, 2013 to 2024). Spontaneous flow of milk from the breast, unassociated with childbirth or nursing. "In those years, the ability of thyrotropin-releasing hormone (TRH) to stimulate the release of prolactin (PRL) in addition to TSH was also recognized, thus explaining the presence of high serum levels of PRL and the occurrence of galactorrhea in hypothyroid patients." (PMID 35207645, 2022).
goiter (3 papers, 2015 to 2021). Enlargement of the thyroid gland usually caused by lack of iodine in the diet, hyperthyroidism, or thyroid nodules. "In addition, the elevated serum levels of TSH and TRH in goiter rats were decreased by their treatments (P < 0.05)." (PMID 28713435, 2017). "In PTU-reduced goiter rats, TH levels are reduced and TRH levels are elevated." (PMID 28713435, 2017). "It is possible that the response to activation of TRH receptors on cell membrane is abnormal, which might explain the reduced TSH response to TRH and the increased incidence of goiter in even euthyroid patients with MD." (PMID 26175917, 2015).
hypopituitarism (3 papers, 2023 to 2024). A condition of diminution or cessation of secretion of one or more hormones from the anterior pituitary gland. "The strengths of this study lie within the high volume of TRH tests performed and the systematic use of tests in all patients at risk of developing hypopituitarism." (PMID 37850100, 2023). "Taking the limited availability of TRH into account, basal prolactin levels can be used in the first step and prevent unnecessary use of TRH stimulation test in most of the patients with hypopituitarism." (PMID 39037546, 2024). "TRH tests have routinely been part of pituitary stimulation tests performed for the diagnosis of pituitary insufficiency at the pituitary referral center at AalborgUH." (PMID 37850100, 2023). "Since all pituitary stimulation tests performed for the hypopituitarism diagnosis at our pituitary referral center have routinely included a TRH test, we aimed to examine the value of such TRH testing in the diagnosis of CH in patients with known pituitary disease." (PMID 37850100, 2023).
Infertility (3 papers, 2021 to 2024). "The authors of the study concluded that decreased serum oestradiol levels and altered PRL secretion after TRH administration in infertile patients with minimal/mild endometriosis were related to ovulatory dysfunction and infertility in this group of patients without tubal occlusion." (PMID 39407928, 2024).
Influenza infection (3 papers, 2024 to 2025). "Furthermore, we found that persistent TCR signaling was needed for the maintenance of TRH cells, and selective ablation of B cell–derived MHCII caused partial reduction of lung TRH levels after influenza infection." (PMID 38345472, 2024). "In this study, we have explored the cellular and molecular cues modulating lung TRH persistence after influenza infection in C57BL/6 mice." (PMID 38345472, 2024). "In this study, we have gone on to examine the roles of Ag persistence, B cells, and TLSs in regulating the development and maintenance of TRH cells after influenza infection." (PMID 38345472, 2024). "Correspondingly, decreased TRH cells resulted in impaired adaptive immunity, rendering the host significantly vulnerable to heterologous influenza reinfection." (PMID 38345472, 2024). "This led us to investigate the requirement of a TLS for the maintenance of TRH cells after influenza infection." (PMID 38345472, 2024). "Influenza infection leads to more widespread and long-lasting inflammation, possibly resulting in a greater capacity for the tissue to support a full-fledged germinal center response and leading to the subsequent development of TRH." (PMID 41256356, 2025). "Importantly, in influenza‐infected lungs, TRH cells retain the ability to differentiate into Th1 effectors and express high levels of Tcf1, a transcription factor associated with self‐renewal and stem‐like properties." (PMID 40815083, 2025). "Furthermore, selective ablation of B cell–derived MHC class II resulted in partial reduction of lung TRH cell number after influenza infection." (PMID 38345472, 2024). "Interestingly, we found IL-21 VFP+ TRH cells interacting with B cells in the TLS at 28 days after influenza infection." (PMID 38345472, 2024). "Interestingly, TRH cells are colocalized with B cells in lung tertiary lymphoid structures (TLSs) after influenza infection." (PMID 38345472, 2024). "An example is seen during influenza infection, where heterogeneous lung‐resident CD4 T cell subsets, including TRH and Th1 cells, are found in and around iBALT." (PMID 40815083, 2025). "We found that IL-21hi cells exhibited the highest expression levels of Il21, Bcl6, and Cxcr5 but not Foxp3, compared with other cell populations, suggesting that TRH cells but not regulatory T cells express IL-21 in the lung after influenza infection." (PMID 38345472, 2024).
lung carcinoma (3 papers, 2010 to 2020). "TRH methylation has been reported in pancreatic cancer, lung cancer and clear cell renal cell carcinoma." (PMID 30081853, 2018). "In lung cancer patients cortisol, TRH, TSH and GH serum level and all the lymphocyte subsubsets variation (except for CD4) showed loss of circadian rhythmicity." (PMID 20565977, 2010). "In this study we evaluated differences among healthy subjects and subjects suffering from lung cancer in the 24-hour secretory profile of melatonin, cortisol, TRH, TSH, FT4, GH, IGF-1 and IL-2 and circadian variations of lymphocyte subpopulations." (PMID 20565977, 2010).
pancreatic cancer (3 papers, 2018 to 2023). "One study found that TRH was substantially methylated in pancreatic cancer cell lines by employing microarrays coupled with methyl-CpG targeted transcriptional activation (MeTA-array) and methylation-specific PCR." (PMID 37766209, 2023).